DNMT1 (DNA methyltransferase 1)
Diseases named in the same sentence as DNMT1 in open-access papers (continued):
Sharing a sentence is not in itself a finding about the gene and the disease.
cancer (continued). "Compared to NOK cells, sh-DNMT1 cancer cells also exhibited more pronounced hypomethylation than sh-NC cells; the majority of these differential hypomethylation sites were at CpG island shores and gene bodies." (PMID 38755637, 2024). "Specifically, DNMT1, typically regarded as a proto-oncogene in various cancers, including KIRC, plays a critical role in DNA methylation." (PMID 38794205, 2024). "It has been demonstrated that in various types of cancers, DNMT1 and DNMT3B act as the leading catalyzers of TSGs methylation silencing." (PMID 38504782, 2024). "Our findings indicate that DNMT1 overexpression contributes to the initiation of oral malignant transformation and facilitates the malignant behavior of cancer cells, resulting in the growth of OSCC tumors." (PMID 38755637, 2024). "UHRF1 and DNMT1, which are central regulators of DNA maintenance methylation, are often reported to be highly expressed in cancer cells." (PMID 38297314, 2024). "We then use genomics and bioinformatics to precisely describe the DNA demethylation dynamics in these cells, leading to the conclusion that UHRF1 maintains DNA methylation in cancer cells not only by stimulating DNMT1." (PMID 38580649, 2024). "DNMT1 is primarily involved in maintaining the pre-existing methylation pattern during DNA replication and the pattern during normal and cancer cell replication." (PMID 38225241, 2024). "Analysis of human samples revealed a correlation between oral malignant transformation, elevated DNMT1 expression, and accumulating cancer-specific DNA hypomethylation." (PMID 38755637, 2024). "Previous studies have also reported decreased levels of DNMT1 expression across various cancer tissue types, supporting our findings." (PMID 39598359, 2024). "Inhibitors targeting epigenetic factors have been explored for cancer therapies and have undergone clinical trials, including DNA methyltransferase 1 inhibitors, histone deacetylase inhibitors, and histone methyltransferase inhibitors." (PMID 38520019, 2024). "In a wide range of cancers, DNA methyltransferases (DNMTs) such as DNMT1, DNMT3a, and DNMT3b have been shown to exhibit overexpression and initiate and maintain DNA methylation at promoter regions." (PMID 38773164, 2024). "In this study, we precisely simulated DNMT1-targeted interventions in cancer cells and validated their potent efficacy in suppressing tumor growth in an OSCC mouse model." (PMID 38755637, 2024). "Proteasomal removal of DNMT1-DPCs formed following aza-dC treatment of cancer cells was also SUMO dependent." (PMID 38254974, 2024). "Taken together, these results implied that the DNMT1-induced GSK3β inactivation promotes cancer cell death through abnormal glycogen metabolism." (PMID 38755637, 2024). "sh-DNMT1-transfected cancer cells exhibited a notably reduced tumorigenic ability, as indicated by decreased tumor growth, reduced cell proliferation and augmented cell apoptosis." (PMID 38755637, 2024). "In this study, we evaluated the antitumor efficacy of co-targeting G9a and DNMT1 enzymes and its potential as a cancer drug sensitizer." (PMID 39488528, 2024). "To further figure out how DNMT1 remodeled global DNA hypomethylation in OSCC, we compared sh-DNMT1 cancer cells to sh-NC cells using a DNA methylation 850 k chip." (PMID 38755637, 2024). "Functional inactivation of PRC2 via oncohistone mutation (H3 K27M) was also observed in pediatric gliomas, suggesting that it is possible to set up a tumor context-specific liability for therapeutic intervention via DNMT1 inhibitors in selective cancer types." (PMID 39056791, 2024). "Compounds 2 and 4 showed the best DNMT1 inhibitory activity, but only compound 4 was able to inhibit the growth of several cancer cell lines." (PMID 39595939, 2024). "A reduction in the phosphorylation levels of CDK1/2/3 and Rb was observed in sh-DNMT1 cancer cells compared to sh-NC cells, confirming the additional inhibition of CDK2-Rb signal transduction." (PMID 38755637, 2024).
cancer (continued). "Strikingly, sh-DNMT1 cancer cells exhibited extensive and nearly complete genome-wide DNA hypomethylation." (PMID 38755637, 2024). "First, we assessed the DNMT1 expression in 31 different cancers and found that expression in AML ranked the highest out of 31 cancer types." (PMID 37573395, 2023). "With DNMT1 deletion and knocking down of DNMT1 protein, the doses that inhibited a half of cancer cells were all higher than 10 μM." (PMID 37045940, 2023). "We provide evidence that Snhg15, a cancer-related lncRNA, recruits DNMT1 to the Ncam1 promoter through RNA/DNA triplex structure formation and the interaction with DNMT1." (PMID 37880732, 2023). "Previous studies have shown that high DNMT1 expression is inversely related to poor survival outcome in patients with GC and other types of cancers." (PMID 37147733, 2023). "Aberrant methylation often results in cancer development through the many-fold expression of DNA methyltransferases (DNMT1, DNMT3a, and DNMT3b) that is comparatively significantly higher than their normal expression in healthy cells." (PMID 36765652, 2023). "The mRNAs and proteins that encode DNMTs (DNMT1, DNMT3A, and DNMT3B) with their related catalytic activities are overexpressed in different cancer types, leading to aberrant behavior compared with normal cells." (PMID 37107631, 2023). "Altogether, our results support the potential use of these newly generated molecules as an approach to block DNMT1 activity and reduce cell viability of cancer cells." (PMID 36609400, 2023). "The results of a series of studies have shown that the combined use of HDAC and DNMT1 inhibitors has a profound effect on the sensitization of chemotherapy-resistant breast cancer cells that can be used as anti-cancer therapies." (PMID 37107631, 2023). "In type I cancer cells, DNMT1 and DNMT3b were preferably upregulated, but downregulated in type II cancer cells." (PMID 37368179, 2023). "DNMTi-mediated inhibition of DNMT1 has been well-studied as an epigenetic treatment strategy for cancer." (PMID 36810560, 2023). "Recent studies have demonstrated the efficacy of simultaneously attenuating G9a and DNMT1 activity in several cancer types with independent pharmacological inhibitors of both targets, and with a novel G9a/DNMT1 dual inhibitor, CM‐272." (PMID 36896891, 2023). "The high expression level of DNMT1 in ductal adenocarcinomas of the pancreas is highly related to the ability of invasion of cancer cells to the adjacent tissue, which almost occurred in an advanced stage with a lower patient survival rate." (PMID 37107631, 2023). "In order to explore the role of DNMT1 in tumor immunity among patients with different cancers, we calculated three indices of ESTIMATE for each sample to assess the fractions of stromal and immune cells." (PMID 37628671, 2023). "In our analysis, both maintenance methylation (DNMT1, DNMT2) and de novo methylation (DNMT3a, DNMT3b) were found to be significantly associated with pan-cancer, resulting in the methylation of CEP55 at positions cg25827255, cg25314624, and cg04026927." (PMID 37887301, 2023). "Previous studies have also demonstrated that DNMT1 inhibition in PDAC reduces cancer cell growth both in vitro and in vivo." (PMID 37759986, 2023). "Our study is in good accord with preclinical observations that pharmacologically disrupting DNMT1 enhances the activity of ICB but suggests an epigenetic pathway presumed to be targeted in cancer cells is also operative in the tumor vasculature." (PMID 37055433, 2023). "One such study has demonstrated that SFN combined with DIM significantly decreased the expression of DNMT1, DNMT3a, and DNMT3b in PC3, LnCAP, and PrEC cells, suggesting the de-methylation of the promoter region of cancer-associated genes." (PMID 36765652, 2023). "The correlation between DNMT1 and 32 immunoinfiltrating cells in 33 different types of cancers was investigated using the Xcell algorithm." (PMID 37628671, 2023).
cancer (continued). "DNMT1 and DNMT3b cooperate to silence genes in human cancer cells, and deletion of DNMT1 and DNMT3b eliminates methyltransferase activity and reduces genomic DNA methylation (global DNA hypomethylation) by greater than 95%." (PMID 37772039, 2023). "An important DNA methyltransferase is DNMT1, relevant for de novo methylation activity in cancer cells and maintaining the methylation state during proliferation." (PMID 37880732, 2023). "We report the effects of DNMT1 gene deletion/disruption (DNMT1−/−) on anticancer activity of a class of DNMTi in vitro, in vivo and in human cancers." (PMID 37045940, 2023). "Silencing of BCL11A gene expression by miR-137 or disruption of BCL11A-DNMT1 (DNA methyltransferase 1) interaction reduced the number of cancer stem cells and inhibited cancer development." (PMID 37185699, 2023). "The up-regulated miR-142-5p directly binds to the 3’-UTR of DNMT1, and then inhibits its expression, thereby indirectly promoting the expression of Maspin and inhibiting the progression of cancer." (PMID 37901333, 2023). "Recently, more evidences had proved that DNMT1 silenced tumour-suppressor gene expression by methylation of promoter DNA sequences, which played critical roles in regulation of drug resistance in cancer chemotherapy." (PMID 36869331, 2023). "For instance, the rate of mRNA expression from DNMT1 is substantially higher in non-cancer liver tissue samples than in chronic hepatitis or cirrhosis samples." (PMID 37107631, 2023). "More importantly, accumulating evidence indicates that DNMT1 acts as an oncogene in several cancers." (PMID 35838271, 2022). "Truly, the expression of DNA methyltransferases DNMT1, DNMT3B and DNMT3A is often upregulated in different cancer cell lines and tissues, thereby causing the CpG islands hypermethylation of various tumor suppressor genes." (PMID 36366451, 2022). "In particular, promoter probes on the active X chromosome which had become de novo methylated in the cancer cells were preferentially resistant to DNMT1 inhibition compared to other chromosomes." (PMID 35654826, 2022). "A positive correlation between DNMT1 expression and cancer cell sensitivity to OXPHOS inhibition was also detected with publicly available data from Depmap." (PMID 36382559, 2022). "The poor outcome of patients with high DNMT1 expression in stromal fibroblasts (P = 0.01204) and cancer cells (P = 0.0187) was confirmed by univariate Cox regression analysis." (PMID 35719957, 2022). "To date, aberrant DNA methylation has been also shown to play an important role during carcinogenesis in pancreatic ductal adenocarcinoma (PDAC), with approximately 80% of cancer overexpressing the DNMT1 protein." (PMID 36091786, 2022). "Excessive poly(ribosyl)ation activity in cancer cells poly(ADP-ribosyl)ates DNMT1 and renders its activity; TET1 is similarly poly(ADP ribosyl)ated, which is one of the causes of hypermethylation of DNA in these cells." (PMID 35327610, 2022). "The oncogenic role of DNMT1 in a variety of cancers, including BC, has received considerable attention." (PMID 35880568, 2022). "This is potentially significant as DNMT1 has been shown to be necessary for cancer stem cell maintenance and tumorigenesis." (PMID 34561554, 2022). "Qualitative modeling was then performed to unfold the cellular events involved in the epigenetic, that is, DNMT1-mediated silencing of RUNX3 that leads to cancer invasion." (PMID 35898303, 2022). "Knockdown of MLL4 leads to a marked decrease in DNMT3A and DNMT1 levels in several human cancer lines we examined." (PMID 36323669, 2022). "It was subsequently concluded that the overexpression of DNMT1 and DNMT3A in cancer was associated with aggressive behavior and hypermethylation status of pituitary adenomas." (PMID 36091786, 2022).
cancer (continued). "The results revealed that the onset of oncogene c-myc introduces pathogenesis in the system and its consistent activation along with persistent suppression of TSG RUNX3 hyperactivates DNMT1 leading to cancer metastasis." (PMID 35898303, 2022). "Next, we sought to investigate the predictive value of DNMT1 expression levels in cancer cells as well as their stromal fibroblasts as a candidate biomarker for clinical outcome of patients with LABC." (PMID 35719957, 2022). "At the same time, in an in vitro study of curcumin in several human cancer cell lines, curcumin induced some global DNA hypomethylation and altered the expression of three DNMTs: DNMT1, DNMT3A, and DNMT3B." (PMID 36499286, 2022). "While in vitro and in vivo experiments have shown that DNMT1 inhibitor 5-AzaC has antitumor activities in several types of cancer, there is a need for optimization of treatments targeting DNMT1 activity." (PMID 35402240, 2022). "For example, a knockout of DNMT1 led to a reduction of cancer stem cell markers such as high expression levels of ALDH (aldehyde dehydrogenase), CD44+ and CD24+ in colon cancer cell lines." (PMID 35563709, 2022). "Biallelic expression of IGF2 is frequently observed in cancers due to DNA methyltransferase 1 (DNMT1)-mediated de novo methylation of the ICR, a process called loss of imprinting (LOI)." (PMID 35974000, 2022). "Combined with other studies on DNMT1 functions in cancer, these findings strongly indicate that DNMT1 is a core driver gene in tumour progression." (PMID 36273188, 2022). "Our study found that RMI2 is related to DNA methylation in multiple types of cancer, among which BRCA, STAD, UCEC is associated with four DNA methylation genes (DNMT3L, DNMT3B, DNMT3A, DNMT1)." (PMID 35552266, 2022). "DNMT1 is crucial for faithfully maintaining methylation patterns in human cancer cells and DNMT1 KO leads to severe mitotic defects and even cell death." (PMID 36059621, 2022). "Noteworthily, DNMT1 promotes the self-renewal capacity of PDAC cancer stem cells which are always resistant to conventional chemotherapy and radiotherapy." (PMID 35838271, 2022). "Taken together, WK-23 is worth developing as DNMT1-selective therapy for the treatment of malignant tumour." (PMID 35670075, 2022). "It is also noteworthy that aberrant over-expression of DNMT1 has been documented in various malignancies, which highlights the significant impact on cancer-related epigenetic silencing of tumor suppressor genes." (PMID 35255904, 2022). "ARPC2 expression was more closely related to DNMT1, which showed a positive correlation in 19 types of cancer and an inverse correlation in four cancer types, but was less closely associated with DNMT3L." (PMID 35733852, 2022). "The RT-qPCR method revealed that EGCG triggered anti- cancer epigenetic alterations, including downregulation of epigenetic regulators DNMT1, HDAC1, HDAC2, and G9a." (PMID 35327559, 2022). "Some results also showed that DNMT1 regulated epithelial–mesenchymal transition and cancer stem cells to promote prostate cancer (PCa) metastasis." (PMID 36091786, 2022). "DNMT1 plays a key role in DNA methylation and is thought to play a role in the signaling mechanisms in cancer development." (PMID 34561554, 2022). "An emerging body of evidence is forming in the literature that implicates the role of enzymes such as BRD4 and DNMT1/DNMT3B as epigenetic drivers of cancer and epithelial to mesenchymal transition." (PMID 35143483, 2022). "A schematic model depicting the stepwise process of replication and methylation of TSG RUNX3 by DNMT1 and its subsequent influence on various cancer signaling pathways was established using the literature-driven information." (PMID 35898303, 2022). "In many solid tumours, overexpressed DNMT1 has been proven to induce cancer growth or proliferation and drug resistance." (PMID 35838271, 2022).
cancer (continued). "It is also responsible for stabilizing DNMT1, which is essential for cancer progenitor cell maintenance and tumorigenesis." (PMID 35938161, 2022). "They concentrate on inhibitors of cancer stem cells’ signaling pathways, DNA (cytosine-5)-methyltransferase 1 (DNMT1), and histone deacetylase (HDAC) inhibitors." (PMID 35269636, 2022). "This function of NF-κB as an “active repressor” acting through local recruitment of the DNMT1 enzyme and subsequent hypermethylation of tumor suppressor gene promoters under specific cytotoxic stimuli has already been described in several cancer types." (PMID 35267594, 2022). "We performed a pan-cancer analysis of DNMT1 expression, and we found that DNMT1 was upregulated in several different tumor types." (PMID 33500531, 2021). "In summary, even though detailed molecular mechanism behind CCDC26-mediated DNMT1 localization still remains to be investigated, our study provides an insight into the role of CCDC26 in cancer as well as a novel lincRNA mechanism of DNMT1 regulation." (PMID 33851096, 2021). "Considering the accumulated literature on the decreased global methylation in cancer cells due to the reduced gene expression level of DNMT1, the lower expression of DNMT1 in GBM cell lines is in harmony with previously published data." (PMID 34345539, 2021). "In both in vitro and in vivo models, TdCyd and FdCyd potently deplete DNMT1 in cancer and concomitantly inhibit tumor growth." (PMID 34452630, 2021). "DNMT1 inhibitors are currently widely studied as epigenetic drugs for cancer treatment, and two DNMT inhibitors, azacytidine and decitabine, have been approved by the FDA for certain cancer treatments." (PMID 34001246, 2021). "DNMT1 is overexpressed in many types of cancer and plays an important role in tumorigenesis through the epigenetic silencing of many TSGs." (PMID 35052383, 2021). "In our study, DNMT1 was upregulated in various cancers, especially in HNSCC tumor tissues compared with adjacent tissues." (PMID 33500531, 2021). "We assessed the expression of four methyl transferases genes (DNMT1,2,3,4) in pan-cancer and investigated their correlation with THUMPD1." (PMID 34762107, 2021). "This switching is thought to involve a mechanism in which a component secreted by peripheral astrocytes suppresses DNMT1, a methyltransferase of cancer cells." (PMID 34299050, 2021). "DNMT1 (maintaining DNA hypermethylation of specific genes) is currently the most important target for epigenetic cancer therapy." (PMID 33436584, 2021). "DNMT1 is closely related to the occurrence and development of various diseases, including several types of cancers, as it affects the methylation levels of CD4+T cell-related genes, thereby inhibiting the immune response 81-84." (PMID 34512165, 2021). "Several studies have revealed an inverse relation between P21 and DNMT1 concentrations in normal and cancer cells." (PMID 33498667, 2021). "In normal cells, the protein level of P21 is much higher than DNMT1, whereas in cancer cells the relation is opposite." (PMID 33498667, 2021). "Resveratrol treatment has inhibited DNA methyltransferases (DNMTs) including DNMT1, DNMT3a, and DNMT3b expression and activity in human cancer cells." (PMID 34633989, 2021). "The overexpression also caused a decrease in expression of cancer-promoting factors EZH2, DNMT1, FOXM1, EGFR, PCNA, AURKA, YAP1, and CDH2." (PMID 34595169, 2021). "PD-L1 regulates DNMT1 through the STAT3-signaling pathway and induces DNMT1-dependent DNA hypomethylation to promote development of cancers, thereby resulting in acquired resistance." (PMID 33562324, 2021). "The results showed that levels of most of the immunosuppressive cytokines, such as Arg2, CCL28, DNMT1, and EZH2, were upregulated in the high-risk subtype, suggesting that high-risk A-HCC patients have reduced cancer-immunity cycle activity." (PMID 34512165, 2021).